U8 (U8 small nucleolar RNA )
Synonyms: LOC124900421
Gene: Small nucleolar RNA gene on chromosome 1 (234,593,275 to 234,593,402, forward strand). Ensembl gene ENSG00000212144.
Gene Ontology:
Biological process: RNA processing
Cellular component: nucleolus
Homologues: Orthologues: chimpanzee U8 (94% identical), macaque U8 (88% identical), rabbit U8 (57% identical). Paralogues in human: U8 (82% identical), U8 (80% identical), U8 (78% identical), U8 (77% identical), U8 (76% identical), U8 (75% identical), U8 (73% identical), U8 (72% identical), U8 (71% identical), U8 (59% identical), U8 (56% identical), U8 (55% identical), and 1 more.